AFP (alpha fetoprotein)
Diseases named in the same sentence as AFP in open-access papers (continued):
Sharing a sentence is not in itself a finding about the gene and the disease.
tumor (continued). "Serum AFP levels showed a steep decline following surgery, further validating this as a tumor marker, which was subsequently followed throughout the patient’s treatment course." (PMID 30208947, 2018). "Although serum tumor biomarkers alpha-fetoprotein (AFP), carbohydrate antigen 19–9 (CA19–9) and carcinoembryonic antigen (CEA) have been used in digestive cancer risk prediction, the prediction efficiency remains unsatisfactory." (PMID 29484118, 2018). "Tumour size less than 7 cm (p = 0.03) and serum alpha-fetoprotein (AFP) < 400 ng/ml (p = 0.02) both correlated with improved response with TACE imaging most likely as a reflection of low tumour burden." (PMID 29463228, 2018). "We determined the following variables that were needed to calculate the SNACOR at baseline: tumour size and number, alpha-fetoprotein level, Child-Pugh class, and objective radiological response after the first transarterial chemoembolisation." (PMID 29703174, 2018). "The ability of CTLs induced by AFP antigen epitope polypeptide vaccine was stronger than that of oligopeptide vaccine, specially attacking AFP-positive tumor cells." (PMID 29805966, 2018). "Clinically, differences in AFP production have also beenassociated with gross and histopathologic tumor differences, including differencesin tumor size, multinodular appearance, and vascular invasion." (PMID 29376136, 2018). "Univariate analysis showed that serum AFP level, CA19‐9, tumor size, AST, γ‐GT, and WWOX were in a significant association with OS and RFS of HCC patients." (PMID 29905011, 2018). "For HCC, researchers have found that elevated levels of many tumor markers are associated with poor prognosis in patients with HCC, such as alpha-fetoprotein, neutrophil to lymphocyte ratio, and platelet to lymphocyte ratio." (PMID 30687735, 2018). "In univariate analysis of OS and cumulative recurrence, USP4 expression, serum AFP level, vascular invasion, and tumor size emerged as significant independent prognostic factors (P < 0.05 for all)." (PMID 29396555, 2018). "Similar to Dr. Cetin’s report, AFP seemed to be more sensitive for tumor follow-up compared to CA-125." (PMID 29933751, 2018). "AFP has been reported to promote cell proliferation and suppress apoptosis suggesting its role in tumor progression." (PMID 30087805, 2018). "The patient’s tumor aberrantly expressed alpha-fetoprotein (AFP), which served as a serum tumor marker that tracked very closely with disease burden." (PMID 30208947, 2018). "AFP is a single-chain oncofetal glycoprotein tumor antigen, the serum level of AFP indicates a growth-regulatory activity toward developing digestive cancer." (PMID 29484118, 2018). "After treatment, CT showed a 2-cm hypodense nodule at the right subphrenic region and wedge-shaped hypoperfusion over segment 7 of the liver, suspicious tumor seeding, and liver metastasis and serum level of AFP was 1831 ng/ml." (PMID 29933751, 2018). "Positive correlation between fecal Gal-3 and disease severity, tumor progression, and biomarkers AFP and CEA, respectively, was also observed." (PMID 29849497, 2018). "As the most widely used serum tumor markers, alpha-fetoprotein (AFP), carbohydrate antigen 19–9 (CA19–9) and carcinoembryonic antigen (CEA) have been in application since the 1970s." (PMID 29484118, 2018). "The results of tumor markers evaluation (AFP – alpha-fetaprotein, β-hCG - beta subunit of human chorionic gonadotropin, CA125 - cancer antigen 125, LDH - lactate dehydrogenase) were available for 38 girls (69.09%)." (PMID 30165903, 2018). "Univariate analysis demonstrated that tumour response was significantly associated with LPFS and RFS and that Child-Pugh classification, AFP level, AJCC stage, and tumour response were significantly associated with OS (p < 0.05)." (PMID 29423102, 2018). "The most frequently reported MVI-associated risk factors are alpha-fetoprotein (AFP), tumor size, tumor number, and histological differentiation." (PMID 29514674, 2018).
tumor (continued). "A large expression distance was associated with a higher alpha fetoprotein (AFP) level, tumor weight, advanced histological and pathological stages, and vascular invasion." (PMID 30046116, 2018). "The genetic correction effect on serum AFP should be considered in the clinic application of such tumor biomarkers." (PMID 29696820, 2018). "High GSTP1 expression was correlated with OS and DFS in the AFP concentration ≤ 400 ng/ml, single tumor number, tumor diameter > 3cm, and PVTT-present subgroups." (PMID 29507666, 2018). "The promotion of tumor proliferation of AFP/AFPR is dependent on the CAMP-PKA pathway and the induction of Ca2+ influx." (PMID 29805966, 2018). "Immunohistochemically, the tumor was focally positive for alpha-fetoprotein (AFP) and beta-catenin in the cell membrane." (PMID 29974291, 2018). "We analyzed the correlation between the surrogates of tumor burden (number and size of tumor, serum AFP level) and 10 noninvasive models." (PMID 30305679, 2018). "The patient’s disease burden tracked closely to serum levels of alpha-fetoprotein (AFP) expressed by the tumor and served as an accurate tumor marker." (PMID 30208947, 2018). "HCC patients with lower AFP and smaller tumor size were more likely to have higher GSTP1, which was correlated to better OS and DFS." (PMID 29507666, 2018). "With regard to tumour markers, alpha fetoprotein was increased prior to orchiectomy in three cases and beta chorionic gonadotropin in one." (PMID 30367648, 2018). "As a result, AFP, TNM stage, tumor stage and distant metastasis were significantly associated with the survival rate of HCC patients." (PMID 30560088, 2018). "Low FBP1 expression was significantly correlated with higher AFP level, satellite nodules, portal vein tumour thrombus, and advanced tumour stage." (PMID 30429463, 2018). "Univariate analysis showed that SML; serum level of total bilirubin ≥1.5 mg/dL, albumin < 3.5 g/dL, and AFP ≥ 20 ng/mL; maximum tumor diameter ≥ 30 mm; and progressive disease in response to treatment were significantly associated with poor OS." (PMID 30041616, 2018). "Independent predictors of survival included tumour size (P < 0.001), baseline alpha-fetoprotein level (P < 0.001) and Child-Pugh class (P < 0.004)." (PMID 29703174, 2018). "Briefly, the serum iron levels <15.1 μmol/l was a significant risk factor for the survival of HBV- related HCC (HR = 2.28, 95% CI, 1.82–2.87; P < 0.001) together with higher AFP levels, larger tumor size and worse BCLC stages." (PMID 29467672, 2018). "Tumor markers of Alpha-fetoprotein, (AFP), Cancer Antigen 125 (CA-125), Cancer Antigen-19.9 (CA19.9), and Carcinoembryonic Antigen (CEA) were all within limits." (PMID 30567078, 2018). "Serum tumor markers were obtained: alpha fetoprotein, 71.8 ng/mL (normalrange, up to 8.0 ng/mL); human chorionic gonadotropin (hCG), 2,003 mUI/mL (normalrange, inferior to 5.0 mUI/mL), and lactate dehydrogenase, 546 UI/L (normal range, to 246 UI/L)." (PMID 30241168, 2018). "While tumor-derived AFP (tAFP) contains >80% of AFP-L3, cord blood serum-derived AFP (nAFP) contains less than 5% of AFP-L3." (PMID 30400822, 2018). "Competing mortality rates were compared in patient subgroups stratified by AFP, metastasis, vascular invasion, multiple tumor, tumor size, and HBsAg-positive values." (PMID 29435900, 2018). "Elder age (≥60 years), unmarried status, severe TNM stage, positive AFP, large tumor size (≥ 2 cm), high fibrosis score were regarded to be significant risk factors for poor overall prognosis." (PMID 30445928, 2018). "As marker of tumour biology, the decrease of AFP after treatments has been related to post-transplant outcome." (PMID 29425151, 2018). "The detection and screening of alpha-fetoprotein (AFP) tumor marker, carcinoembryonic antigen (CEA), squamous cell carcinoma antigen (SCC), total prostate specific antigen (TPSA), and free prostate-specific antigen (FPSA) were all normal." (PMID 29851791, 2018).
tumor (continued). "AFP reinforced by transabdominal ultrasonography has also been shown to be extremely valuable parameter giving key information on the ongoing tumour process and should be then added in the clinical-biological monitoring of patients." (PMID 29805811, 2018). "Serum AFP levels increase by 20–80% in HCC patients and are strongly associated with tumor aggressiveness." (PMID 30355653, 2018). "Chen and co-workers demonstrated that the presence of ascites, a high tumor grade and AFP >1000 ng/ml were independently correlated with MVI by logistic regression analysis in patients with HBV-related cirrhotic HCC." (PMID 30254101, 2018). "In conclusion, our study provided the first evidence that RBBP5 was conspicuously overexpressed in HCC and was associated with Ki-67 expression, AFP, TNM stage, tumor size, and poor prognosis." (PMID 30533424, 2018). "Further analysis indicated that hsa-miR-210 was positively associated with AFP level, pathological grade, TNM stage, tumor stage and vascular invasion." (PMID 30560088, 2018). "Cut-offs for tumour number of ≥3 and alpha-fetoprotein concentration of ≥48.3 ng/ml were derived from the corresponding ROC curves." (PMID 29895820, 2018). "A variety of cancers are known to produce tumor-shed antigens (TSAs), i.e. CEA, CA125, CA15-3, AFP, etc., that enhance tumor cell survival and/or metastasis." (PMID 29016358, 2017). "Serum tumor markers including alpha-fetoprotein (AFP), carbohydrate antigen 19-9 (CA 19-9) and carcinoembryonic antigen (CEA) were all within normal limit." (PMID 28376766, 2017). "The other predictive variables were well-known tumor-related factors, including a large tumor diameter, multiple nodules, an incomplete capsule and an AFP level > 20 ng/ml." (PMID 28464845, 2017). "A growing number of investigations of AFP as a tumour-specific biomarker have concluded that AFP is an important target for cancer treatment." (PMID 27913752, 2017). "Risk factors for worse 5-year disease-free survival on univariable analyses comprised pretransplant alpha-fetoprotein (p < 0.001), total tumor volume (p < 0.001), tumor size (p = 0.013), number (p = 0.006), and poor differentiation (p = 0.035)." (PMID 28695391, 2017). "A recent meta-analysis indicated that SCCA and SCCA-IgM exhibit moderate diagnostic accuracy as novel tumor makers of HCC, although the value of the combination of SCCA/SCCA-IgM and AFP requires further investigation." (PMID 28077782, 2017). "Similar results were found in the multivariate analysis adjusted by AFP, tumor size and tumor number, and differentiation." (PMID 28348581, 2017). "In HCC, aberrant methylation of VIM has been suggested to be associated with primary HCC and correlated with clinicopathological variables, including alpha-fetoprotein levels and maximal tumor size." (PMID 28333958, 2017). "Other significant prognostic parameters included the CRP, AST, ALB, ALP, GGT, and AFP levels, the tumor diameter and vascular invasion." (PMID 28355305, 2017). "By univariate analysis, we found many significant prognostic predictors for DFS or OS of HCC, including preoperative Fib, Child-Pugh stage, AFP, size of largest tumor, tumor number, macro- and micro-vascular invasion." (PMID 27935864, 2017). "Patients with high expression of USP22 and low expression of Smad4 significantly has lower AFP, smaller tumor size and higher TNM stage." (PMID 28445968, 2017). "Next, we performed quantitative PCR analysis of five tumor markers such as AFP, NOPE (neighbor of Punc 11), a novel TM of the liver, β2 microglobulin (β2M), carcinoembryonic antigen (CEA), or neuron-specific enolase (NSE)." (PMID 28422070, 2017). "Serum ALT, tumor size, tumor differentiation, tumor number, and GFAT1 expression were incorporated in the nomogram model for OS of the HCC patients, while serum AFP, tumor size and GFAT1 expression were considered for RFS." (PMID 28186970, 2017).
tumor (continued). "The results of tumor markers evaluation (AFP – alpha-fetoprotein, β-hCG - beta subunit of human chorionic gonadotropin, CA125 - cancer antigen 125, LDH - lactate dehydrogenase) were available for 122 girls (57.01%)." (PMID 28893324, 2017). "Recently, Zheng SS proposed the Hangzhou criteria, which include tumor diameter, histological level and AFP level." (PMID 29207647, 2017). "Univariate analysis revealed that age (P = 0.044), serum AFP levels (P = 0.008), tumor size (P = 0.001), stage (P < 0.001), differentiation (P < 0.001), and ABO blood group (P = 0.001) were prognostic indicators for overall outcome." (PMID 28667286, 2017). "Diffuse type (P < 0.001), macro vascular invasion (P < 0.001) and late stage tumours (P < 0.001) had AFP over 400 ng/ml." (PMID 29207969, 2017). "We investigated relationships between gross classification and tumor factors, including alpha-fetoprotein (AFP) level, tumor size, number of nodules, tumor cell differentiation, MVI, and intrahepatic metastasis." (PMID 28392502, 2017). "Meanwhile, serum AFP (HR, 1.964; 95% CI, 1.130 to 3.410, P = 0.017), tumor size (HR, 2.130; 95% CI, 1.338 to 3.391, P = 0.001), and GFAT1 expression (HR, 2.370; 95% CI, 1.417 to 3.964, P = 0.001) were determined as independent prognostic factors of RFS." (PMID 28186970, 2017). "We show here that the AFP level was an independent risk factor associated with tumor differentiation, TNM stage, tumor size, and survival of patients with HCC." (PMID 28993684, 2017). "Tumour nodularity (P = 0.026), AFP level (P = 0.008), and early stage (P = 0.042) were individual predictors of survival." (PMID 29207969, 2017). "Multivariate analysis according to the Cox regression hazard model adjusted by AFP, tumor size and tumor number, and differentiation was next performed to evaluate the independent predictive effect of rs7959378 polymorphism on RFS and OS." (PMID 28348581, 2017). "We calculated positive rates of the F-M, P-M, H-M and FPHA-M models in HCC and BLD patients with different levels of elevated serum AFP, clinical stages and tumor sizes." (PMID 29228649, 2017). "The baby was discharged at 1 month of age with a 3-month tumor screening schedule by abdominal ultrasonography and serum alpha-fetoprotein (AFP)." (PMID 29190888, 2017). "We previously discovered that glypican-3 (GPC3, also known as MXR7) is overexpressed in HCC and is correlated with high alpha-fetoprotein, high tumor grade, and high tumor aggressiveness." (PMID 29113314, 2017). "After a stepwise removal of variables, the following six risk factors remained as significant predictors for OS: AFP, ALP, tumor size, metastasis, vascular invasion, and TACE with H101." (PMID 28728568, 2017). "Many prog nostic factors of HCC have been identified, including serum alpha-fetoprotein (AFP) levels, tumor size, tumor multifocality, microvascular invasion, completeness of tumor removal and tumor metastases, etc." (PMID 29371967, 2017). "Chlorella vulgaris has chemopreventive effect by downregulating the expression of tumour markers M2-PK, OV-6, AFP and TGF-β, in HCC-induced rats." (PMID 29268718, 2017). "In contrast, AFP only correctly determined 64.7 percent (11/17) of the patients with small tumor (Median 2.7, ranging from 1.5 to 2.9)." (PMID 28657540, 2017). "HCC with total tumour diameter more than 5 cm (P = 0.013) and diffuse type tumours (P = 0.002) had higher AFP levels." (PMID 29207969, 2017). "GGT > 53U/L (OR = 2.360, 95% CI 1.287-4.325, P = 0.005), AFP > 200 ng/ml (OR = 2.544, 95% CI 1.399-4.628, P = 0.002) and tumor size > 3.5cm (OR = 2.938, 95% CI 1.585-5.447, P = 0.001) were independent predictors for MVI." (PMID 28977857, 2017). "Decreased GABPA expression was correlated with alpha-fetoprotein levels (P = 0.001), tumor grade (P = 0.017), and distant metastasis (P = 0.021)." (PMID 28549418, 2017).
tumor (continued). "Patients with the S87 mutation were characterized by larger tumour size, higher TNM stage, and higher serum AFP and intrahepatocellular cccDNA levels." (PMID 28640739, 2017). "MVI index = 0.293 x (number of tumors) + 0.283 x (size of the largest tumor in cm) + 0.164 x loge(pre-transplant alpha-fetoprotein concentration in ng/ml)." (PMID 28057916, 2017). "Okuda staging and BCLC are based on tumor size and serum albumin and bilirubin levels, and the CLIP score predicts HCC based on the Child-Pugh stage, AFP level and tumor morphology." (PMID 29383172, 2017). "FABP5 positivity correlated with the histologic presence of microvascular invasion (P = 0.0001), tumor differentiation (P = 0.0337), tumor size (P = 0.0001), tumor markers such as AFP (P = 0.0022) and PIVKA‐II (P = 0.0025)." (PMID 28374947, 2017). "In multivariate analysis, after adjusting for alpha-fetoprotein > 400ng/mL, Child-Pugh class B, and tumor extension > 50% of liver volume, TACE was independently associated with a decreased mortality risk(HR 0.19, 95% CI: 0.08–0.42)." (PMID 29190692, 2017). "Numerous biomarkers of hepatocarcinogenesis have been identified in recent researches, and AFP has been recognized as the standard HCC tumour biomarker for a long time." (PMID 28821282, 2017). "65.8% of the tumor tissues showed hypermethylation, which was associated with tumor grade, TNM stage and distance metastasis, higher level of AFP, and poorer treatment response." (PMID 28404963, 2017). "We also found a weak positive correlation between PLCE1 and AFP mRNA expression in HBV-related HCC tumor tissues (r=0.107, P=0.019)." (PMID 28418898, 2017). "Additional sub-analyses were performed according to different alpha-fetoprotein (AFP) level and tumor-node-metastasis (TNM) stage." (PMID 27935871, 2017). "We started by obtaining PBLs that screened negative for HLA-A2 molecules from healthy donors followed by co-culture with T2/AFP cells to generate AFP peptide specific tumor-reactive T cells." (PMID 28904691, 2017). "A greater reduction in serum AFP levels after neoadjuvant chemotherapy was correlated with smaller tumor size after neoadjuvant chemotherapy (correlation coefficient = 0.41; P = 0.02)." (PMID 28851352, 2017). "In conclusion, diagnostic efficacy of the combination of 3-miRNA panel and AFP was powerful for HCC diagnosis, especially in early tumor screening and low-level AFP patients." (PMID 28079796, 2017). "The level of tumor markers, including AFP, CEA, CA199, CA125, and CA242, was slightly increased in 6 patients, but none were diagnosed as malignant SPN." (PMID 29094047, 2017). "In our cohort, sex, PCDH20, AFP, and tumor number were found to be four crucial independent prognostic factors for HCC." (PMID 27935871, 2017). "Key features of both scores, including tumour morphology, size, AFP levels, metastases and PVT have all been shown to predict survival in patients on sorafenib." (PMID 28212535, 2017). "Tests that are widely available include tumor markers, such as AFP, and various imaging techniques, including US, CT, and MRI of the abdomen." (PMID 28620797, 2017). "We identified that TNM stage (P=0.016), tumor number (P=0.012), AFP>400 (ng/ml) (P=0.008), MVI (P=0.024), tumor size (P<0.001) and under-expression of MIR22HG (P=0.021) were significant prognostic factors associated with HCC patients." (PMID 29371967, 2017). "A rise of postoperative serum AFP level normally indicates tumor recurrence, whereas normal serum AFP level cannot exclude recurrent tumor." (PMID 29254216, 2017). "According to the multivariate Cox proportional hazards model, the pretreatment NLR, tumor diameter and pretreatment alpha-fetoprotein (AFP) levels were independent predictors of OS." (PMID 28355305, 2017).